RAET1L (retinoic acid early transcript 1L)
Description:
Binds and activates the KLRK1/NKG2D receptor, mediating natural killer cell cytotoxicity.
Synonyms: ULBP6
Tractability: Antibody: UniProt places it where antibodies can reach, with high confidence; its Gene Ontology location is reachable by antibodies, with high confidence; UniProt predicts a signal peptide or a membrane-spanning region; the Human Protein Atlas places it where antibodies can reach. PROTAC: ubiquitination databases record sites on it.
Gene: Protein-coding gene on chromosome 6 (150,018,334 to 150,025,532, reverse strand). Ensembl gene ENSG00000155918.
Subcellular location: Cell membrane; Endoplasmic reticulum
Subcellular location (Human Protein Atlas): Plasma membrane; Vesicles
Pathways (Reactome):
Metabolism of proteins: Post-translational modification: synthesis of GPI-anchored proteins
Gene Ontology:
Molecular function: protein binding; natural killer cell lectin-like receptor binding; receptor ligand activity
Biological process: antigen processing and presentation of endogenous peptide antigen via MHC class I via ER pathway, TAP-independent; antigen processing and presentation of endogenous peptide antigen via MHC class Ib; natural killer cell mediated cytotoxicity; positive regulation of T cell mediated cytotoxicity; signal transduction
Cellular component: plasma membrane; endoplasmic reticulum; external side of plasma membrane; extracellular region
Genetic constraint (gnomAD): Loss-of-function variants: 12 observed, 16.08 expected, observed/expected ratio (o/e) 0.75, 90% interval 0.48 to 1.21. The upper end of that interval is the gene's LOEUF score, 1.21, which puts it in group 5 of 6, group 1 being the genes least tolerant of losing a copy. Missense variants: 203 observed, 212.69 expected, observed/expected ratio (o/e) 0.95, 90% interval 0.85 to 1.07. Synonymous variants: 63 observed, 76.67 expected, observed/expected ratio (o/e) 0.82, 90% interval 0.67 to 1.01.
Homologues: Orthologues: pig ULBP1 (39% identical), mouse Ulbp1 (23% identical), zebrafish mhc1laa (14% identical), zebrafish mhc1lda (14% identical), zebrafish mhc1lfa (14% identical), tropical clawed frog mhc1-uea (13% identical), zebrafish mhc1lla (13% identical), zebrafish mhc1lga (12% identical), zebrafish mhc1lba (12% identical), zebrafish mhc1lja (12% identical), zebrafish si:dkey-52p2.5 (11% identical), zebrafish mhc1lca (11% identical). Paralogues in human: ULBP2 (94% identical), RAET1G (87% identical), ULBP1 (60% identical), ULBP3 (53% identical), RAET1E (32% identical), HLA-E (24% identical), HLA-A (24% identical), HLA-C (24% identical), HLA-B (23% identical), HLA-F (22% identical), HFE (22% identical), HLA-G (22% identical), and 10 more.
Diseases named in the same sentence as RAET1L in open-access papers:
RAET1L is named in the same sentence as 15 diseases in open-access papers, as found by Europe PMC text mining. Sharing a sentence is not in itself a finding about the gene and the disease. The quoted sentences say what the papers report.
Alopecia universalis (1 paper, 2025). Alopecia universalis is the most severe form of alopecia areata, an inflammatory disease of the hair follicle, which is characterized by a complete loss of hair of the scalp and all the hair-bearing areas of the body. "The credible set was composed of 36 variants, which were most significantly associated with alopecia universalis and overlapped with the RAET1L gene (which encodes ULBP6)." (PMID 40116579, 2025).
basal cell carcinoma (1 paper, 2025). A carcinoma involving the basal cells. "Although not statistically significant, other cancer phenotypes, such as squamous cell carcinoma, melanoma, and hematologic malignancies, exhibited a similar directionality to basal cell carcinoma with the four RAET1L missense variants." (PMID 40116579, 2025).
colon adenocarcinoma (1 paper, 2022). "A report showed that RAET1L together with ULBP1, ULBP2, ULBP3 had the high diagnostic values in colon adenocarcinoma (COAD)." (PMID 36294477, 2022).
diabetes (1 paper, 2014). "Ontological classification demonstrates that these 14 genes are associated with diabetes (ALMS1P; RAET1L; GYS1; RBM47; EFR3B), cancer (RPL27A; SPAM1; PTCH1; ZNF277; USP35; CDC86), or metabolism (C3orf15; AOC2; GOT1)." (PMID 24885560, 2014).
lung squamous cell carcinomas (1 paper, 2025). "RAET1L is highly expressed in head and neck, esophageal, cervical, and lung squamous cell carcinomas." (PMID 40116579, 2025).
tumor (6 papers, 2021 to 2025). "ULBP2 and RAET1G (which encodes ULBP5), which share the highest sequence homology with RAET1L, also exhibit similar expression profiles within the tumor microenvironment." (PMID 40116579, 2025). "The RAET1L (ULBP6) gene has been shown to encode the ligand for the immunoreceptor NKG2D, an important mediator of anti-tumor activity." (PMID 38610938, 2024). "Our differential expression analysis results showed that ULBP1, ULBP2, ULBP3, and RAET1L had significant differential expression in COAD tumor and adjacent normal tissues." (PMID 33909599, 2021). "The mRNA level of CR2, INSL4, FGF5, RAET1L and TNFRSF13B was upregulated in LUAD tumor tissues compared with paired normal tissues whereas AGER was downregulated." (PMID 36294477, 2022). "The near-exclusive expression of RAET1L (ULBP6) in malignant cells within the tumor microenvironment distinguishes it from nontumor-specific NKG2DLs such as MICA/B, which may translate to an improved therapeutic window for ULBP6-targeting therapies." (PMID 40116579, 2025).
cancer (3 papers, 2014 to 2025). A tumor composed of atypical neoplastic, often pleomorphic cells that invade other tissues. "Although RAET1L is associated with inverse risks for cancer and inflammatory diseases, the directionality of its expression based on our genetics data alone in either disease class is unclear." (PMID 40116579, 2025). "By leveraging 23andMe, Inc.’s large-scale germline genetic database, we identified RAET1L (ULBP6) as a promising I/O drug target, given its inverse risk associations with cancer and immunologic disorders." (PMID 40116579, 2025). "Given the genetic association of RAET1L with cancer, we analyzed its mRNA expression using The Cancer Genome Atlas to confirm its relevance in a broad range of cancers." (PMID 40116579, 2025). "Specifically, retinoic acid early transcript 1L (RAET1L) was upregulated only in female cancer compared with normal tissue." (PMID 38610938, 2024). "This suggests that the variants present in the associated signals may alter not only RAET1L expression but also ULBP1, ULBP2, and ULBP3 and affect the risk of cancer and immune diseases." (PMID 40116579, 2025).
RAET1L also shares sentences with these, for which no sentence is quoted: asthma (1 paper); colorectal cancer (1); COVID-19 (1); hematologic malignancies (1); immune diseases (1); melanoma (1); ovarian carcinoma (1); squamous cell carcinoma (1).